SPTBN2 (spectrin beta, non-erythrocytic 2)
Diseases named in the same sentence as SPTBN2 in open-access papers (continued):
Sharing a sentence is not in itself a finding about the gene and the disease.
lung adenocarcinoma (3 papers, 2021 to 2022). A carcinoma that arises from the lung and is characterized by the presence of malignant glandular epithelial cells. "Combined with bioinformatics and cell experiments, SPTBN2 may become a novel target of lung adenocarcinoma." (PMID 35371219, 2022). "However, the relationship between SPTBN2 and lung adenocarcinoma (LUAD) has never been reported." (PMID 34745988, 2021). "The roles played by β-III-spectrin, also known as spectrin beta, non-erythrocytic 2 (SPTBN2), in the occurrence and development of lung adenocarcinoma (LUAD) have not been previously examined." (PMID 34745988, 2021).
Alzheimer disease (2 papers, 2023 to 2024). A progressive, neurodegenerative disease characterized by loss of function and death of nerve cells in several areas of the brain leading to loss of cognitive function such as memory and language. "Reduced levels of m7G modification on Sptbn2 mRNA due to METTL1 deficiency inhibit stability and translation, leading to impaired hippocampal neurogenesis and spatial memory in adult mice, ultimately contributing to Alzheimer's disease(AD)." (PMID 39155349, 2024).
autism (2 papers, 2020 to 2025). Persistent deficits in social interaction and communication and interaction as well as a markedly restricted repertoire of activity and interest as well as repetitive patterns of behavior. "Spectrin members of the cytoskeletal scaffold proteins α2 spectrin (SPTAN1) and β3 spectrin (SPTBN2) were significantly decreased in children with autism." (PMID 40779003, 2025).
bladder cancer (2 papers, 2021 to 2023). "The high expression of ABCB9, SPTBN2, GULP1, IGF1, P4HB, NES and DPYSL2 and the low expression of ANXA6, OAS1, RAD9a, DNASE2B and FANCF would be beneficial to the prognosis of bladder cancer patients." (PMID 37845668, 2023).
cholangiocarcinoma (2 papers, 2022 to 2024). A carcinoma that arises from the intrahepatic biliary tree (intrahepatic cholangiocarcinoma) or from the junction, or adjacent to the junction, of the right and left hepatic ducts (hilar cholangiocarcinoma). "The results from xCELL suggest that expression of SPTBN2 negatively correlates with the infiltration levels of most immune cells in ovarian serous cystadenocarcinoma and cholangiocarcinoma (p < 0.05)." (PMID 38684762, 2024). "A growing body of evidence has extensively proven that SPTBN2 plays a vital role in the diagnosis of cholangiocarcinoma." (PMID 35968508, 2022).
lung carcinoma (2 papers, 2014 to 2021). "The human lung cancer cell lines A549 and H1299 were selected for the transfection of small interfering RNA (siRNA) targeting SPTBN2 (si-SPTBN2), and the knockdown efficiency was evaluated by RT-qPCR." (PMID 34745988, 2021). "The expression of SPTBN2 in non–small cell lung cancer (NSCLC) ranked 13th among cancer cell lines based on the CCLE database." (PMID 34745988, 2021).
asthma (1 paper, 2015). "Whereas, the second study showed two genes – CNKSR3 and SPTBN2 which expression in PBMCs differentiates between AIA and ATA, but neither CNKSR3 nor SPTBN2 has described relationship with asthma and aspirin." (PMID 26646719, 2015).
benign neurofibromas (1 paper, 2021). "Moreover, SPTBN2 has been detected in more than 90% of malignant peripheral nerve schwannomas (MPNST), but not in normal peripheral nerve and benign neurofibromas." (PMID 34887379, 2021).
Cerebellar atrophy (1 paper, 2021). Cerebellar atrophy is defined as a cerebellum with initially normal structures, in a posterior fossa with normal size, which displays enlarged fissures (interfolial spaces) in comparison to the foliae secondary to loss of tissue. "The 13 patients exhibited a homogeneous NPCA phenotype with global cerebellar atrophy, and all of them harbored SPTBN2 substitutions in heterozygosis." (PMID 33801522, 2021).
cerebral palsy (1 paper, 2020). A group of disorders affecting the development of movement and posture, often accompanied by disturbances of sensation, perception, cognition, and behavior. "Seven infantile onset cases have been described of which four have a predominantly ataxic cerebral palsy phenotype - three with the same mutation Arg480Trp within the SPTBN2 gene (NM_006946)." (PMID 31721007, 2020).
cervical squamous cell carcinoma (1 paper, 2024). A squamous cell carcinoma arising from the cervical epithelium. "In addition, SPTBN2 correlated with grades of cervical squamous cell carcinoma and endocervical adenocarcinoma (CESC), LIHC, STAD, HNSC, and PAAD (p < 0.05); while it significantly correlated with stages of KIRP, uterine carcinosarcoma, LUAD, LIHC, and THCA (p < 0.05)." (PMID 38684762, 2024).
colon adenocarcinoma (1 paper, 2024). "SPTBN2 was also found to be closely related to certain tumor subtypes, including KIRP, colon adenocarcinoma (COAD), and SKCM (p < 0.05)." (PMID 38684762, 2024).
colon cancer (1 paper, 2021). "Five genes (FAS, VWA5A, SPTBN2, PCK1, and TIMP1) significantly affect the prognosis of patients with colon cancer." (PMID 34957118, 2021). "Finally, the ARGPI was constructed based on five apoptosis genes (FAS, VWA5A, SPTBN2, PCK1, and TIMP1), which can effectively improve the prediction of colon cancer progression." (PMID 34957118, 2021).
developmental and epileptic encephalopathy (1 paper, 2022). An epilepsy associated with developmental impairment that may be due to either the underlying etiology or the superimposed epileptic activity, or both. "Mendelian disease-gene links are increasingly being recognized for the spectrin genes, with SPTAN1, SPTBN1, SPTBN2 and SPTBN4 linked to neurological diseases such as developmental and epileptic encephalopathy (DEE), ataxia, hereditary spastic paraplegia, and hereditary motor neuropathy." (PMID 36238261, 2022).
esophageal carcinoma (1 paper, 2024). A primary or metastatic malignant neoplasm involving the esophagus. "For DSS, high expression of SPTBN2 was also associated with poorer survival in most cancers, including KIRC, PAAD, stomach and esophageal carcinoma (STES), and stomach adenocarcinoma (STAD) (p < 0.05)." (PMID 38684762, 2024). "Methylation levels of SPTBN2 were found to differ significantly between KIRP, PRAD, LIHC, KIRC, Lung squamous cell carcinoma (LUSC), PAAD, HNSC, BLCA, Esophageal carcinoma (ESCA), BC, THCA, LUAD, COAD, and UCEC and their corresponding normal tissues (p < 0.05)." (PMID 38684762, 2024).
heart failure (1 paper, 2019). Inability of the heart to pump blood at an adequate rate to meet tissue metabolic requirements. "In the heart, the SPTBN2 and JUP have established roles in mechanical function, and alterations in these proteins are associated with heart failure and cardiomyopathy." (PMID 31792287, 2019).
neuroblastoma (1 paper, 2024). Neuroblastoma (NB) is the most common solid, extracranial childhood tumor. "Following 21 days of treatment with 20 μmol/L of tazemetostat, we observed an induction in GREB1 and SPTBN2, genes previously shown to be transcriptionally repressed by H3K27me3 in neuroblastoma cells." (PMID 38837897, 2024).
non-small cell lung carcinoma (1 paper, 2024). A group of at least three distinct histological types of lung cancer, including non-small cell squamous cell carcinoma, adenocarcinoma, and large cell carcinoma. "Previous studies on SPTBN2 have mainly focused on neurodegenerative diseases, and its role in non-small cell lung cancer (NSCLC) is poorly understood." (PMID 38241838, 2024).
prostate adenocarcinoma (1 paper, 2024). "Cox regression analysis demonstrated that SPTBN2 is significantly correlated with PFI in STES, PAAD, STAD, uveal melanoma (UVM), prostate adenocarcinoma (PRAD), KIRC, and BLCA (p < 0.05)." (PMID 38684762, 2024).
renal angiomyolipoma (1 paper, 2023). "After applying Pearson analysis, we identified five proteins (out of the 34 intersected DE proteins) positively correlated with the maximum renal angiomyolipoma (p < 0.05), namely, PCSK1N, PMEL, HK1, GOT2 and SPTBN2." (PMID 36891236, 2023).
thyroid cancer (1 paper, 2022). "The GSEA results revealed that in TCGA cohort, the cell cycle/apoptosis pathway was closely associated with SPTBN2 expression in thyroid cancer." (PMID 35968508, 2022). "Although bioinformatics studies have revealed that SPTBN2 may be correlated with the initiation and progression of malignancies, the molecular mechanism of SPTBN2 in thyroid cancer has never been investigated." (PMID 35968508, 2022).
type 6 hypomyelination leukodystrophy (1 paper, 2021). "Pathogenic mutations in SPTBN2, KIF1A, and TUBB4A were already known to cause SCA5 (OMIM # 600224), autosomal recessive SPG30 (OMIM # 610357), and both autosomal dominant type 4 dystonia (OMIM # 128101) and type 6 hypomyelination leukodystrophy (OMIM # 612438), respectively." (PMID 33833777, 2021).
tumor (11 papers, 2021 to 2026). "The results indicated that age, gender, SPTBN2 expression, and disease stage were significant independent risk factors for increased tumor size." (PMID 35968508, 2022). "We showed that SPTBN2 was closely associated with tumor size, LNM, and disease stage." (PMID 35968508, 2022). "We performed a single-cell analysis and found that SPTBN2 is significantly enriched in PAAD tumor cells." (PMID 38684762, 2024). "Via various database analysis, up-regulated expression of SPTBN2 was detected in most of the tumor tissues examined." (PMID 38684762, 2024). "In particular, the DNA methylation level of SPTBN2 in PAAD tumor tissues compared with normal samples was significantly reduced (p < 0.05)." (PMID 38684762, 2024). "While SPTBN2 KO alone exhibited a modest reduction in tumor volume and weight compared to the vector control, this difference was not statistically significant." (PMID 38241838, 2024). "SPTBN2 was found to be abnormally expressed at high levels in different tumor types, including PAAD, and at low levels in KIRC tissues." (PMID 38684762, 2024). "Since high SPTBN2 levels were correlated with a poor prognosis in CRC patients, SPTBN2 negative regulation by miR-15b demonstrates its tumour-suppressive role." (PMID 39456841, 2024). "When expression levels of SPTBN2 were compared between 22 types of tumor tissues and corresponding normal tissues in pan-cancer, statistically significant differences were observed." (PMID 38684762, 2024). "The results of the in vitro experiment revealed that in TC cell lines, SPTBN2 downregulation considerably suppressed tumor cell proliferation, the cell cycle, migration, colony formation, and invasion and induced cell apoptosis." (PMID 35968508, 2022). "Specifically, the upregulation of SPTBN2 was correlated with tumor size (P = 0.004), disease stage (P < 0.001), and LNM (P = 0.002)." (PMID 35968508, 2022). "In the univariate logistic regression analysis, age, gender, SPTBN2 expression, LNM, and disease stage were significant risk factors for increased tumor size." (PMID 35968508, 2022). "The HPA and IHC analyses showed that the SPTBN2 protein is significantly differentially expressed between tumor and normal tissues." (PMID 34745988, 2021). "Consistently, the expression of SPTBN2 was significantly elevated in our collected tumor tissues versus that in ADJ tissues (n = 134)." (PMID 34544413, 2021). "The m6A modification of SPTBN2 was much higher in tumor tissues than that in ADJ tissues, which was positively correlated with the LINC01605 expression." (PMID 34544413, 2021). "Subsequently, we analyzed the m6A modification levels of SPTBN2 mRNA in tumor tissues and ADJ tissues using MeRIP-qPCR." (PMID 34544413, 2021). "It was obvious that the tumor volume in the SPTBN2-knockdown group was significantly reduced compared to the control groups, and the tumor weight in the SPTBN2 silencing group was also significantly reduced." (PMID 34887379, 2021). "We found that SPTBN2 was positively correlated with the levels of CC tumor markers CA199 and CEA in patients’ serum." (PMID 34544413, 2021). "In our next analysis, we found that the expression of SPTBN2 was also significantly higher in the tumor tissues of 19 patients with recurrence than in those without recurrence." (PMID 34544413, 2021). "In recent years, increasing evidence has indicated that SPTBN2 is highly expressed in various tumors and plays considerable roles in tumor occurrence and metastasis." (PMID 34745988, 2021). "In addition, expression of SPTBN2 correlates with the proportion of immune and stromal cells in each tumor, suggesting that SPTBN2 levels are closely correlated with immune activation in a variety of tumors such as PAAD (p < 0.05)." (PMID 38684762, 2024). "SPTBN2 also plays a considerable role in both tumor genesis and metastasis." (PMID 38684762, 2024).
tumor (continued). "Notably, when combined with cisplatin, SPTBN2 KO significantly decreased tumor volume and weight compared with the cisplatin monotherapy group, without affecting body weight." (PMID 38241838, 2024). "In addition, compared with normal tissues, methylation levels of SPTBN2 were significantly lower in PAAD tumor tissues, and they significantly negatively correlated with mRNA levels." (PMID 38684762, 2024). "Furthermore, immunohistochemical staining showed that SPTBN2 protein was highly expressed in PAAD tumor cells." (PMID 38684762, 2024). "A single-cell analysis showed that SPTBN2 is highly expressed in tumor cells, which suggests that SPTBN2 may promote cancer." (PMID 38684762, 2024). "When we further investigated the relationship between SPTBN2 expression and tumor stem cell score, a significant positive correlation was observed between SPTBN2 expression and both DNAss and EREG-METHss scores in most malignancies, but especially in PAAD, CESC, and STES (p < 0.05)." (PMID 38684762, 2024). "In addition, in COADREAD and thyroid carcinoma (THCA), SPTBN2 promotes the proliferation and migration ability of tumor cells." (PMID 38684762, 2024). "Similarly, an analysis of the Tumor Immune Evaluation Resource (TIMER) database showed that UCEC (64/531) and SKCM (40/468) had the highest mutation rates of SPTBN2." (PMID 38684762, 2024). "Moreover, the staining intensity of SPTBN2 in tumor tissues was positively correlated with the staining intensity of LINC01605." (PMID 34544413, 2021). "The oncogenic role of SPTBN2 has been rarely investigated, whereas our prognostic analysis demonstrated that patients with higher expression of SPTBN2 suffered from short survival and more advanced tumor stage, which was correlated with its m6A modification." (PMID 34544413, 2021). "Therefore, SPTBN2 may participate in neutrophil-mediated immunosuppression to achieve a tumor promoting effect in PAAD." (PMID 38684762, 2024). "All in all, these data indicated SPTBN2 might be involved in tumor metastasis." (PMID 34887379, 2021). "In addition, over-expressed CLDN4 could partially reverse the effects of SPTBN2 knockdown on tumor progression." (PMID 34887379, 2021). "Based on multi-omics data, the potential for SPTBN2 to serve as a prognostic biomarker of PAAD and a predictor of immune status and immunotherapy response of the tumor microenvironment (TME) is investigated in PAAD patients." (PMID 38684762, 2024). "The results above delineate the alteration of SPTBN2 and BCL2L1 in view of tumor immune modulation mediated by CCL27 and CCR10, resulting in a reduced abundance of CD4+ T cells and dendritic cells." (PMID 34179092, 2021). "In the following exploration, we have focused on the roles of SPTBN2 and BCL2L1 in the tumor microenvironment from the perspective of immune modulation by retrieving data from the TIMER database." (PMID 34179092, 2021). "Based on these results, we speculate that SPTBN2 overexpression and KRAS activation may interact to promote tumor growth and inhibit the penetration of CD8 + T cells in PAAD." (PMID 38684762, 2024). "Furthermore, in patients with PTC in TCGA cohort and our local validated cohort (48 PTC patients), clinicopathological characteristics (tumor size, LNM, and disease stage) showed a high positive correlation with the high expression of SPTBN2." (PMID 35968508, 2022). "More potential for lymph node metastases and advanced tumor stage was observed in CC patients with high expression of SPTBN2, but SPTBN2 expression was independent of the diameter and histological type of the tumor tissues." (PMID 34544413, 2021). "SPTBN1, which is an important paralog of SPTBN2, and other nonerythroid spectrins exert either oncogenic or tumor suppressor activities by affecting various cancer-related biological processes, including cell differentiation, DNA damage repair, and epithelial-to-mesenchymal transition." (PMID 35968508, 2022).